EGFR (epidermal growth factor receptor)
Diseases named in the same sentence as EGFR in open-access papers (continued):
Sharing a sentence is not in itself a finding about the gene and the disease.
breast carcinoma (continued). "Treatment with cetuximab, a humanized antibody to EGFR, reduced transmigration through a simulated blood–brain barrier and extended survival of mice injected with brain-colonizing breast cancer cells." (PMID 23217186, 2012). "Taken together, our data shows that EBP50 can suppress EGF-induced proliferation of breast cancer cells by inhibiting EGFR phosphorylation and blocking EGFR downstream signaling in breast cancer cells." (PMID 22476347, 2012). "In ER- breast cancer, those characterized with high expression of EGFR and low expression of Th1-mediated pathway-related markers such as interleukin-12 and interferon-gamma were found to have a poor prognosis." (PMID 22420471, 2012). "Functional cross-talk between Wnt-triggered signaling and the EGFR system has been previously identified in other cancer cells of epithelial origin such as breast cancer cells." (PMID 23285165, 2012). "Mechanism-based studies showed that GPER transactivates EGFR in breast cancer cells as well as in thyroid, endometrial and ovarian cancer cell lines." (PMID 23273253, 2012). "To determine if the impact of EGFR signaling in the bone microenvironment is similar to that of breast cancer cells, we used a mouse preosteoblastic cell line MC3T3 as a model to compare receptor phosphorylation induced by exogenous ligand treatment." (PMID 22276166, 2012). "Unsaturated fatty acids activate EGFR signaling in a rodent model of breast cancer as well as human endothelial cells." (PMID 22761823, 2012). "To verify this finding is due to EGFR inhibition and not off target effects of the shRNA construct, we examined MCSF-1 levels in a panel of breast cancer cell lines following treatment with the small molecule EGFR inhibitor PD153035 or PAR34." (PMID 22276166, 2012). "Taken together, these data suggest a role for Met in clinical resistance to EGFR TKIs in breast cancer through EGFR/Met crosstalk mediated by tumor-stromal interactions." (PMID 22788954, 2012). "Gene amplification and increased copy number of the EGFR gene associated with the response rate to EGFR-targeted drugs in NSCLC, breast cancer and colon cancer." (PMID 22815900, 2012). "Several molecular targets have been suggested to be suitable for optical detection of breast cancer such as the epidermal growth factor receptor (EGFR), vascular endothelial growth factor (VEGF), and (human epidermal growth factor receptor 2) HER2." (PMID 22695343, 2012). "Some of these proteins (EGFR, P-cadherin, α-basic crystalline, and moesin) are independent poor-prognosis markers in breast cancer." (PMID 22082486, 2012). "In breast cancer for example, overexpression of the epidermal growth factor receptor, EGFR, is a common finding in invasive ductal carcinomas, where EGFR-positive tumors represent an adverse prognostic marker." (PMID 24704979, 2012). "It is likely that the EGFR on breast cancer cells controls the expression of many additional cytokines and growth factors that mediate tumor cell-microenvironment interactions, both in primary tumors and sites of metastasis." (PMID 22276166, 2012). "In a proof-of concept study with lysates from breast biopsies, the assay allowed to classify breast cancer samples in accordance to clinically the relevant EGFR cut-off level." (PMID 22577549, 2012). "This sensitivity is in conflict with the observed clinical resistance to EGFR TKIs in breast cancers." (PMID 22788954, 2012). "Met phosphorylation has also been identified as a contributor to EGFR TKI resistance in breast cancer." (PMID 22788954, 2012). "It was also proven that enhanced EGFR/erbB2 signaling in tamoxifen resistant breast cancer cells potentially results from selection for a more stem-like phenotype." (PMID 23554768, 2012). "Recent studies suggest that GPR30 expression is associated with a poor prognosis, and that this is due to the GPR30-mediated transactivation of the EGFR in breast cancer." (PMID 23163984, 2012).
breast carcinoma (continued). "Whereas the 22-Mbp region 7p22.1-p15.3 contains many genes, the second gained region on chromosome 7 contains only one gene, the epidermal growth factor receptor (EGFR); EGFR is a well-known and important gene in breast cancer initiation and progression." (PMID 22429330, 2012). "The version of nanobioconjugate with two antibodies (the lead drug) showed the most dramatic decrease in the expression of p-Akt signal, which supports the idea that the lead drug inhibited breast cancer growth by blocking the EGFR-regulated pathway." (PMID 22355336, 2012). "IQSEC1 links epidermal growth factor receptor signaling to ARF6 activation to induce breast cancer invasion." (PMID 23202957, 2012). "Recent studies have shown that GPR30 exerts its effects through the activation of the epidermal growth factor receptor (EGFR) transduction pathway in endometrial cancer, breast cancer, and thyroid cancer cells." (PMID 23163984, 2012). "In HER2 dominant breast cancer cells, lengthy exposure to the EGFR inhibitors gefitinib or erlotinib or the HER2 inhibitor AG-825 led to the upregulation of HER3 and Akt phosphorylation in correlation with HER3 translocation from the nucleus to the membrane." (PMID 23198146, 2012). "Previous studies have shown that PA-MSHA to inhibits cellular proliferation and induces apoptosis in human breast cancer cell lines in a dose-dependent manner through EGFR pathway signaling." (PMID 23077664, 2012). "This study showed a regulatory mechanism in which MAPK/ERK signals inhibit EGFR/PI3K/Akt-mediated TF expression in breast cancer MDA-MB-231 cells." (PMID 22534171, 2012). "SHIP2 functions as a positive regulator of the epidermal growth factor receptor/Akt pathway, C-X-C chemokine receptor type 4 expression, and cell migration in breast cancer cells but a negative regulator of keratinocyte migration." (PMID 22121480, 2012). "We analyzed the roles of Epidermal Growth Factor Receptor (EGFR) and Hepatocyte Growth Factor Receptor (Met) in mammary epithelial cells and mammary tumor cells derived from a mutated-ErbB2 transgenic mice." (PMID 23028720, 2012). "While expression of EGFR has been evaluated in canine mammary tumors, brain tumors, nasal carcinomas, and lung tumors, it has yet to be proven as a driver of tumor proliferation in any canine cancer." (PMID 22630170, 2012). "We first visualized, by western-blot analysis, the presence of ErbB2, EGFR and Met in mammary tumor lysates obtained from different mice." (PMID 23028720, 2012). "Compared to female breast cancer CCND1 and EGFR were found to be more frequently amplified in male breast cancer, while in females EMSY and CPD were more often involved and more frequent amplifications of TRAF4 and EMSY were found." (PMID 22527098, 2012). "Due to this inhibitory ability, (+)-aeroplysinin-1 was found to have a strong antitumor effect on EGFR tumor cell lines, in particular blocking the proliferation of EGFR dependent human breast cancer cell lines MCF-7 and ZR-75-1." (PMID 22073013, 2011). "For the MDA-MB-231 breast cancer cells, there was a marked increase in EGFR expression after both 3 and 5 days of hypoxic exposure." (PMID 21320311, 2011). "To date, the effect of blocking oncogenic IGF-1R and EGFR signaling have been studied more extensively in breast cancer lines." (PMID 21776391, 2011). "Epidermal Growth Factor Receptor (EGFR) was found to be increased in plasma samples collected 17 months before breast cancer diagnosis." (PMID 21871081, 2011). "In Western studies, EGFR protein expression has been demonstrated in 7-36% of breast cancer patients, while gene amplification has been found in around 6% of cases and mutations were either absent or extremely rare." (PMID 21702909, 2011). "Although research into the role of ErbB receptor signalling in breast cancer has focused primarily on EGFR and ErbB2, it is becoming increasingly clear that both ErbB3 and ErbB4 also have important roles to play in this disease." (PMID 21396094, 2011).
breast carcinoma (continued). "Anti-HER2 antibody trastuzumab has revolutionised the treatment of patients with EGFR-positive breast cancer, and agents targeting EGFR/HER1 are in use for colorectal cancer therapy as well as for head and neck cancer." (PMID 21982514, 2011). "Women whose breast cancer expressed EGFR, in particular, had frequently more than one metastatic site at the time when the first distant metastases were detected." (PMID 21914172, 2011). "In vivo, AST1306 potently suppressed tumor growth in ErbB2-overexpressing adenocarcinoma xenograft and FVB-2/Nneu transgenic breast cancer mouse models, but weakly inhibited the growth of EGFR-overexpressing tumor xenografts." (PMID 21789172, 2011). "Collectively, these findings identified the novel intracellular targets Src/Akt and EGFR/ERK1/2 that are differentially affected by nicotine exposure to facilitate breast cancer progression." (PMID 22085699, 2011). "In summary, our findings suggest that Src and EGFR play pivotal roles in regulating nicotine-treated breast cancer cell proliferation and survival." (PMID 22085699, 2011). "The results obtained establish a functional role for Kp signaling in promoting breast cancer cell motility and invasion, two critical processes required for metastasis, via cross-talk with EGFR." (PMID 21738726, 2011). "We have also discovered that GPR54 directly complexes with EGFR, and that stimulation of breast cancer cells with either Kp-10 or EGF regulates the endocytosis of both GPR54 and EGFR." (PMID 21738726, 2011). "To date, the effect of blocking oncogenic IGF-1R and EGFR signaling have been studied more extensively in breast cancer cell lines." (PMID 21776391, 2011). "Cytosolic phospholipase A2α (cPLA2α) activity provides the substrate for cyclooxygenase-dependent PG release, and we have previously found that cPLA2α expression correlated with EGFR/HER2 over-expression in a small number of breast cancer cell lines." (PMID 21119660, 2011). "This study aimed at investigating the existence of a cross-talk between nAChR and EGFR for the promotion of breast cancer growth." (PMID 22085699, 2011). "Several therapies targeting EGFR (cetuximab, gefitinib and erlotinib) are in clinical use for advanced breast cancer." (PMID 21980430, 2011). "Activation of the Stat3 pathway in breast cancer can occur through many pathways, including those of EGFR, HER2, IL-6 receptors, IL-11 receptors, and progesterone receptors." (PMID 21689417, 2011). "Though nominally classified as a diagnosis of exclusion (thus "triple-negative"), TNBC tumors frequently (72-75%) overexpress epidermal growth factor receptor (EGFR), whereas only a minority (16%) of ER-positive breast cancers overexpress EGFR." (PMID 21396117, 2011). "In various trials, EGFR gene amplification in breast carcinomas was different, ranging between 0.8-28 percent." (PMID 22132735, 2011). "Studies addressing EGFR protein expression and gene amplification in Saudi breast cancer patients are extremely scanty and the results reported have been mostly non-conclusive." (PMID 21702909, 2011). "The epidermal growth factor receptor (EGFR) is an available target of effective anti-EGFR therapy for human breast cancer." (PMID 22132735, 2011). "The concept of breast cancer prevention through EGFR inhibition has been explored previously; in fact, EGFR inhibitors have been successfully used for the prevention of breast cancer in experimental mouse models." (PMID 21396117, 2011). "Increased expression of EGFR/HER2 and decreased expression of ERα are molecular markers associated with resistance to endocrine therapy in breast cancer." (PMID 21119660, 2011). "Recently, we reported that IRS-1 can interact with EGFR, resulting in loss of recruitment of IRS-1 by IGF-IR and reducing signalling via this receptor in an ER+, tamoxifen-resistant MCF-7 breast cancer cell line." (PMID 21939528, 2011).
breast carcinoma (continued). "Knockdown of the GPCR scaffolding protein, β-arrestin 2, inhibited Kp-10-induced EGFR transactivation as well as Kp-10 induced invasion of breast cancer cells via modulation of MMP-9 secretion and activity." (PMID 21738726, 2011). "In this study, we have investigated the impact of EPA, DHA and AA on breast cancer cell growth, on cell signalling in apoptosis and on epidermal growth factor receptor (EGFR) activity." (PMID 21569413, 2011). "An interesting observation of our study is the apparent dual roles of versican G3 domain in modulating breast cancer cell resistance to chemotherapy and EGFR targeting therapy." (PMID 22096483, 2011). "Brain metastases have been found to be associated with HR-negative and triple-negative (ER-, PgR-, HER2-) breast cancers, EGFR expression, low Bcl-2, and breast cancer HER2 expression and presence of HER2 amplification." (PMID 21914172, 2011). "More studies on EGFR in breast cancer are needed from different regions of Saudi Arabia before our assumption can be confirmed, however." (PMID 21702909, 2011). "EGFR signaling appears crucial to the sensitivity or resistance of versican expressing breast cancer cells to chemotherapy." (PMID 22096483, 2011). "As is clear with other tumor types such as glioblastoma and breast cancer, secondary genetic alterations such as PTEN loss can mitigate the response to EGFR or HER2 inhibitors." (PMID 21394210, 2011). "Nevertheless, it has been shown that EGF stimulation enhances EGFR mitochondrial localization in MDA-MB-231 breast cancer cells and that mitochondrial EGFR interacts with cytochrome c oxidase subunit II (CoxII) in an EGFR Y845-dependent manner." (PMID 21388543, 2011). "EGFR is an interesting target for tumour therapy, because it is over-expressed in many human tumours such as lung and breast cancers." (PMID 21569413, 2011). "Our study reveals the existence of a potential, regulatory network governed by the interaction of nicotine and nAChR that integrates the conventional, mitogenic Src and EGFR signals for breast cancer development." (PMID 22085699, 2011). "There are only a few reports regarding the overexpression of EGFR, with these studies indicating 8-36% of breast cancers over express this protein." (PMID 22132735, 2011). "Preclinical studies have shown that reduced PTEN expression increases cancer cell survival and proliferation, and has been associated with resistance to EGFR inhibitors in NSCLC and colon cancers, and resistance to trastuzumab in breast cancer." (PMID 22095222, 2011). "CEER was able to detect single-cell level expression and phosphorylation of human epidermal growth factor receptor 2 (HER2) and human epidermal growth factor receptor 1 (HER1) in breast cancer (BCa) systems." (PMID 22172159, 2011). "Increased activation of EGFR and dysregulated expression of versican contributes towards a more aggressive human breast cancer phenotype." (PMID 22096483, 2011). "It has been reported that HDACi decreased the EGFR mRNA stabilityin ER-negative human breast cancer cells." (PMID 21464950, 2011). "In one study, EGFR gene amplification and/or high EGFR expression were demonstrated as biological predictors of poor prognosis in breast carcinoma." (PMID 22132735, 2011). "We were unable to detect SGLT1 RNA or protein expression in our systems, despite the fact that the EGFR was expressed in the mammary carcinoma cell lines." (PMID 21826239, 2011). "Most breast cancers express β-ARs, and there is a striking correlation between EGFR levels and β2-AR levels." (PMID 21476970, 2011). "Overexpression of the epidermal growth factor receptor (EGFR) has been identified in cancer cells from different types of tumors, including cancer of the breast, lung, brain, stomach, colon and ovary." (PMID 23554696, 2011). "Taken together with studies in breast cancer showing that EGFR signalling can regulate Cten expression, a wider EGFR-Kras-Cten signalling pathway can be inferred." (PMID 21698197, 2011).
breast carcinoma (continued). "It is also known that the EF-enhanced directional migration correlates well with the expression level of EGFR/ErbB1 in breast cancer cells." (PMID 21998723, 2011). "An immunohistochemical panel including ER, PR, HER2, Ck5/6 and EGFR antibodies was used as a surrogate for gene expression profiling to classify the 231 breast cancer specimens." (PMID 21702909, 2011). "EGF stimulates the proliferation of breast cancer cells by binding to EGFR which is one of the oncogenes of breast cancer." (PMID 22174624, 2011). "IGF-1R signaling is important for the survival of breast cancer cells and crosstalk between IGF-1R and EGFR signaling pathways have been implicated in the development of more aggressive disease." (PMID 21854628, 2011). "Of the 36 women who had breast cancer expressing EGFR, 15 (41.7%) were first diagnosed with lung metastases as compared with 20 (12.5%) of the 160 women whose cancer was EGFR-negative (P < 0.0001)." (PMID 21914172, 2011). "The presence of activating mutations conferring a better prognosis has been reported with EGFR mutations in non-small cell lung cancer (NSCLC) and with PIK3CA mutations in breast cancer." (PMID 21352589, 2011). "Signal transduction cascades downstream of epidermal growth factor (EGF) receptor (EGFR) isoforms (e.g., EGFR & HER2) have been associated with breast cancer development and resistance to anticancer agents." (PMID 21881167, 2011). "In our current investigation, we demonstrated that EGFR was activated and subsequently internalized in breast cancer cells in response to nicotine treatment, accompanied by the cascade of the phosphorylation of several intracellular effector kinases." (PMID 22085699, 2011). "The assay was applied to single breast cancer cells to analyze the chromosomal region centred by the therapeutical relevant EGFR gene." (PMID 22140428, 2011). "The epidermal growth factor receptor (EGFR), a member of the ErbB family of receptor tyrosine kinases, is an important therapeutic target for several epithelial tumors, including breast cancer." (PMID 21738726, 2011). "In this study, we demonstrated a novel signaling mechanism by which nicotine exposure activated Src to sensitize epidermal growth factor receptor (EGFR)-mediated pathways for breast cancer cell growth promotion." (PMID 22085699, 2011). "EGFR signaling plays an important role in cell proliferation and tumorigenesis in a variety of cancers, including breast cancer." (PMID 21980430, 2011). "In breast cancer, Cten is positively regulated by c-Erb-B2 protein – this is over-expressed in a specific subset of breast cancers due to gene amplification and is a part of the Epidermal Growth Factor Receptor (EGFR) signalling pathway." (PMID 21698197, 2011). "Upregulation of EGFR signaling plays an important role in breast cancer development and cooperation between nAChR and EGFR has been suggested in cancer progression." (PMID 22085699, 2011). "For cervical cancer, our results suggested that potential drugs are likely to involve the EGFR pathway; and with the breast cancer dataset, we identified candidates that are involved in prostaglandin inhibition." (PMID 21305029, 2011). "EGFR protein expression as assessed by immunohistochemistry has been demonstrated in 7-36% of breast cancer patients, while gene amplification as assessed by CISH or FISH has been found in around 6% of cases." (PMID 21702909, 2011). "Particular in breast cancer, EGFR signaling seems to be upregulated in basal-like tumors (triple-negatives), especially in cells with stem cell like features." (PMID 22140428, 2011). "A higher rate of EGFR missense mutations (45.8%) was reported in hereditary BRCA1/2 positive breast tumours, which are typically triple-negative, than in sporadic breast cancers (14.6%)." (PMID 22192147, 2011).